BMP4 (bone morphogenetic protein 4)
Diseases named in the same sentence as BMP4 in open-access papers (continued):
Sharing a sentence is not in itself a finding about the gene and the disease.
glioma (continued). "Hence, it is not surprising to see lack of superior growth inhibition for the BMP-4 producing virus in differentiated glioma lines since BMP-4 is believed to target undifferentiated, stem cell-like cells." (PMID 23800258, 2013). "Furthermore, in western blot analysis, the BMP4 protein was upregulated in low-grade glioma tissues when compared with high-grade glioma tissues (P = 0.001)." (PMID 24099560, 2013). "But in clinical cases, the effect of BMP4 expression on the prognosis for glioma is still unclear." (PMID 24099560, 2013). "That exhibited the predomination of beneficial effects over detrimental effects of BMP4 in gliomas." (PMID 23590708, 2013). "Immunohistochemistry was used for validating the expression of BMP4 in another 77 glioma samples." (PMID 23590708, 2013). "We conclude that BMP4 is an independent prognostic factor for glioma." (PMID 24099560, 2013). "Interestingly, we found that the expression of BMP4 was significantly related to distant glioma metastasis." (PMID 24099560, 2013). "The expression status of BMP4 in gliomas was evaluated by RT-PCR and immunohistochemistry." (PMID 24099560, 2013). "BMP4 expression was observed in 36.98% (233/630) of the glioma sections." (PMID 24099560, 2013). "Immunohistochemical analyses showed that BMP4 localized in the cytoplasm of glioma cells." (PMID 24099560, 2013). "Furthermore, BMP4 mRNA was upregulated in low-grade glioma tissues when compared with high-grade glioma tissues (P = 0.01)." (PMID 24099560, 2013). "The expression status of bone morphogenetic protein 4 (BMP4) in gliomas is still unclear by now." (PMID 24099560, 2013). "At present, the expression status of BMP4 in gliomas and the mechanism of BMP4 action are unclear, and studies investigating the function and mechanism of this molecule in the biological behavior of gliomas are still rare." (PMID 24099560, 2013). "Therefore, BMP4 has been indicated as a potential anti-glioma drug candidate." (PMID 34357080, 2021). "Finally, BMP4 can convert glioma CSCs into normal glia cells." (PMID 30310855, 2018). "Moreover, BMP4 was downregulated in high grade glioma when compared with low grade glioma." (PMID 24877113, 2014). "However, the prognostic and molecular features of gliomas with BMP4 expression is still unclear." (PMID 23590708, 2013). "Protective genetic changes in glioma include increased expression of ADGRB3/1, IL12B, DYRKA1, VEGFC, LRRC4, and BMP4." (PMID 39022728, 2024). "Extensive studies reported genetically engineered MSCs with tumour necrosis factor-related apoptosis-inducing ligand TRAIL, BMP4, and PTEN efficiently suppressed glioma tumour growth and induced apoptosis." (PMID 38698968, 2024). "LncRNA PVT1 promotes the expression of BMP2 and BMP4 by regulating GREM1 expression and promoting glioma progression." (PMID 35113786, 2022). "For instance, the TGF-β signaling pathway was found to be altered through glioma progression, as observed by an increase in the level of BMP molecules, including BMP3 and BMP4, as well as their targets, such as Smad1/5/8 and Id." (PMID 33671331, 2021). "In gliomas, BMP2 and BMP4 have been proposed to be a potential predictor for the prognosis of patients." (PMID 34357080, 2021). "BMP4 is the most well-studied BMP member in gliomas, including in vivo and in vitro researches, and has been evidenced against the gliomas’ tumorigenicity through inducing their differentiation into astrocytes and neuronal/oligodendroglia cells." (PMID 34357080, 2021). "On the other hand, HIF1α has been reported to directly upregulate BMP4 expression in various types of cells and indirectly stabilize NOTCH1 protein and activate NOTCH1-HES1 signaling in human glioma stem-like cells and T lymphocytes." (PMID 33015064, 2020). "For instance, Bone Morphogenetic Protein 4 (BMP4)-expressing MSCs were found to efficiently suppress tumor growth and prolong survival of glioma-bearing mice." (PMID 32117924, 2020).
glioma (continued). "Subsequent to the finding that glioma stemness was co-regulated by Twist1 and Sox2, normal neural stem cells that acquired glioma-like invasiveness through the combined FGF2 and BMP4 pathways were found to demonstrate EMT-related features." (PMID 25605251, 2015). "Additional studies employing larger microarray databases available nowadays should confirm the view that the role of BMP4 and BMP7 in glioma differs from that of BMP2." (PMID 24877113, 2014). "There are only limited reports on the role of BMP4 in gliomas focusing on the anti-proliferation effect of BMP4 to stem-like cells and GBM cell lines.In the present study, we found that BMP4 was overexpressed in LGGs." (PMID 23590708, 2013). "Low-grade gliomas express higher levels of BMP4 than high-grade gliomas, correlating to lower mortality rates; this suggests BMP could be a prognostic marker in gliomas." (PMID 36420140, 2022). "Furthermore, upon stimulation with TGF-β1, BMP-4, or BMP-10, their levels remained unaltered in T98G glioma cells." (PMID 33471197, 2021). "Although the status of EGFR was not analyzed, the effect of BMP4 on glioma cells was mediated by its downstream targets, p21CIP1 and ID1 (DNA-binding protein inhibitor 1)." (PMID 32788653, 2020). "Treatment of U251 cells with BMP4 and scrambled siRNA resulted in a rightward shift of the temozolomide IC50 curve, consistent with a protective effect of BMP4 against temozolomide cytotoxicity in glioma cells." (PMID 31602000, 2019). "Our studies detected five proteins that interacted with Fstl1 in glioma using Co-IP and pulldown experiments, i.e., DIP2A, CD14, BMP4, ActR-IIB, and follistatin, and the mRNA levels of MGMT were only increased in GBM cells transfected with DIP2A-specific siRNA (siDIP2A)." (PMID 30542120, 2019). "Thus, the growth factors, e.g., BMP4 and BMP7, which present and play a role in the neuron differentiation and development have been suggested to be of importance for glioma recurrence and these factors should be further investigated for future pharmaceutic targets." (PMID 34357080, 2021). "However, BMP4 mediated differentiation therapies must be used in a patient-specific context since a subset of gliomas do not differentiate in response to BMP4." (PMID 32102285, 2020). "Interestingly, we discovered that the presentation of BMP-4 on these glycopeptide structures alone, without the use of a traditional chemotherapy, resulted in reduced tumor growth and enhanced survival in an orthotopic xenograft pediatric high-grade glioma tumor mouse model." (PMID 41624070, 2025). "Findings demonstrate that despite MSC1 showing anti‐glioma benefits in vitro, engineering of MSC1 with BMP4 did not substantially improve survival against its counterpart suggesting that the technical capability of a donor is necessary, but not sufficient, to ensure therapeutic potency." (PMID 39545093, 2024).
Obesity (41 papers, 2013 to 2026). Accumulation of substantial excess body fat. "We also observed at the mRNA level altered expression of Bmp4, which is also associated with obesity and energy metabolism, to reveal a significant sex effect, where levels were increased in females compared to males." (PMID 38003633, 2023). "Here, we found that deficiency of BMP4 in PVAT accelerated obesity or Ang II-induced hypertension and vascular remodeling." (PMID 36457800, 2022). "As Ahnak deficiency mediates obesity resistance, we proposed possible mechanism that Ahnak cooperates with Bmpr1α, which regulates the BMP4/Smad1/5 signal transduction." (PMID 30154465, 2018). "In our previous study, the serum BMP-4 level was associated with obesity and the presence of metabolic syndrome." (PMID 24170999, 2013). "Multiple studies suggest that BMP4 signaling is important for the recruitment and differentiation of adipocytes and the development of a brown phenotype, which protects against obesity and obesity-linked insulin resistance." (PMID 38339160, 2024). "BMP-4 levels were associated with the visceral adipose tissue and may play a certain role in fat distribution and subclinical hypothyroidism in obesity." (PMID 28376799, 2017). "However, little study has investigated the association of BMP-4 levels with fat distribution in obesity." (PMID 28376799, 2017). "However, if the expression of BMP4 cannot be promoted (e.g., due to genetic defects), individuals might easily enter a state of obesity when the level of BMP4 is negatively associated with BMI." (PMID 33872596, 2021). "Our findings suggest that miR-6402 is a novel anti-adipogenic miRNA that combats obesity by inhibiting the BMP4/BMPR2 signalling pathway and subsequently reducing adipose tissue expansion." (PMID 40028748, 2025). "In the present study, we identified miR-6402 as a novel obesity regulator that targets Bmpr2 and inhibits BMP4/BMPR2-induced adipogenesis." (PMID 40028748, 2025). "Our results indicated that miR-6402 plays an important role in the pathophysiology of obesity by suppressing BMP4-induced adipogenesis." (PMID 40028748, 2025). "Genetic ablation of noggin in mouse preadipocyte and adipocyte reinforces the BMP4 signaling, resulting in uncontrolled adipogenesis as well as obesity." (PMID 36831329, 2023). "BMP4 is increased in patients with metabolic disorders such as DM, obesity, and nonalcoholic fatty liver disease(NAFLD), and its level is negatively associated with insulin sensitivity." (PMID 37370018, 2023). "To investigate the role of PVAT metabolism in obesity-induced hypertension, we measured the BP of two-type BMP4-DKO and the control mice with fed with HFD." (PMID 36457800, 2022). "A previous study showed that serum BMP4 levels are significantly increased in individuals with obesity or MetS and positively correlated with body mass index, waist circumference, and waist-to-hip ratio." (PMID 35477568, 2022). "Recent studies have found that serum BMP4 levels are significantly increased in patients with obesity and metabolic syndrome (MetS), but reduced after weight loss." (PMID 35477568, 2022). "The BMP4 signaling pathway is involved in the pathophysiology of obesity and abnormal glucose metabolism." (PMID 33986800, 2021). "After the initial period on chow diet, we challenged the mice with a high fat diet (HFD) for an additional 12 weeks to induce severe obesity, which increases adipose tissue cell size and BMP4 levels." (PMID 33606810, 2021). "BMP4 is secreted by adipose cells and increases in hypertrophic obesity which plays a key role in regulating adipogenic precursor cell commitment and differentiation." (PMID 34258293, 2021). "BMP4 is secreted by mature adipocytes and increases in hypertrophic obesity, thereby eliciting a positive feedback signal to recruit new adipocytes." (PMID 33910166, 2021). "Studies in non-neoplastic diseases indicate on the relationship between BMP-4 and obesity with metabolic syndrome." (PMID 34501309, 2021).
Obesity (continued). "Another study showed in the case of obesity, BMP4 was able to increase the transformation of adipose tissue." (PMID 33910166, 2021). "As obesity led to an increase in the number of atretic follicles, we wondered if this increase was induced by the abnormal expressions of the genes BMP4, GDF9, or LHX8 that play key roles during ovarian follicular development." (PMID 33282873, 2020). "A small cohort study showed that serum BMP4 levels were significantly increased in individuals with obesity or metabolic syndrome." (PMID 31831718, 2019). "It is conceivable that manipulating BMP4 and/or mTORC1 signaling networks would lead to the development of novel therapeutics for obesity, metabolic syndrome, and NAFLD." (PMID 31831718, 2019). "For instance, mice with genetically increased levels of bone morphogenetic protein 4 are protected from obesity due to a phenotype with sWAT browning, despite BAT accumulating lipids and adapting a beige/brite phenotype." (PMID 29914151, 2018). "The adipose tissue secretes endogenous BMP4, and this is enhanced in obesity, in order to promote the recruitment of new progenitor cells rather than merely expanding available cells and developing a dysfunctional hypertrophic obesity." (PMID 29247377, 2018). "Recent data has certified that BMP-4 plays a role in obesity as BMP-4 is an integral feedback regulator of both white and beige adipogenic commitment and differentiation." (PMID 28376799, 2017). "BMP-4 signaling is involved in the common pathophysiology of obesity and abnormal glucose metabolism." (PMID 28376799, 2017). "A study also found that BMP-4 levels are significantly higher in obesity patients with metabolic syndrome." (PMID 28376799, 2017). "Our study suggested that the serum BMP-4 levels were also significantly positively correlated with BMI in females with obesity." (PMID 28376799, 2017). "Obesity is one of the components of metabolic syndrome and previous study has shown that serum BMP-4 levels were significantly increased in individuals with obesity or metabolic syndrome." (PMID 28376799, 2017). "In the present study, we have demonstrated that BMP4 plays a key role in obesity-induced cardiovascular disease." (PMID 25678859, 2015). "Collectively, our data show that AHNAK promotes adipose tissue development and obesity by potentiating BMP4/SMAD1 signaling and that AHNAK can serve as a novel regulator of metabolic homeostasis." (PMID 26466345, 2015). "This aligns with prior reports linking BMP4 to metabolic diseases, including obesity, diabetes, and hepatic steatosis, suggesting that BMP4 may facilitate PAAD tumorigenesis via metabolic regulation." (PMID 41169612, 2025). "Both adipose expression and serum levels of BMP4 are increased in obesity." (PMID 40780446, 2025). "Imbalance in commitment programming indeed leads to uncontrolled AT expansion as a root of hypertrophic obesity, providing that BMP4 signaling is negatively regulated by the direct binding between BMP4 and their physiological inhibitors, such as noggin and gremlin." (PMID 36831329, 2023). "The attenuated BMP4 signaling not only blunts the commitment program in ASCs, but also represses the adipocytic lipogenesis which further promotes ectopic lipid storage in muscle and liver, explaining why systemic inflammation occurs in obesity." (PMID 36831329, 2023). "The mechanism of how BMP4 participates in promoting obesity is not well understood; the role in adipogenesis may be an important reason." (PMID 33910166, 2021). "In summary, the BMP4 protein has been linked with both obesity and PCOS, which may be responsible for the obesity status of PCOS cases." (PMID 33910166, 2021). "Serum BMP4 levels were significantly increased in subjects with obesity or Mets." (PMID 34258293, 2021). "BMP4 promotes brown adipocyte differentiation and thermogenesis in vivo and in vitro which offers a potentially new therapeutic approach for the treatment of obesity." (PMID 34258293, 2021).
Obesity (continued). "A previous study also showed a relationship between BMP4 and obesity." (PMID 34258293, 2021). "Considering the close association between CHRDL1 and BMP4, the role of BMP4 in PCOS and obesity may point out the potential role and mechanism of CHRDL1 in PCOS or obesity." (PMID 33910166, 2021). "It has been demonstrated that serum level of BMP-4 was positively correlated with obesity." (PMID 32481541, 2020). "Similarly, increased circulating BMP4 in mature mice prevented obesity and insulin resistance, and promoted subcutaneous WAT browning, leading to increased energy expenditure." (PMID 31831718, 2019). "Manipulating BMP4 and/or mTORC1 signaling axis may lead to the development of novel therapeutics for obesity, metabolic syndrome, and NAFLD." (PMID 31831718, 2019). "It was shown that selective brown adipose tissue overexpression of Bmp4 in mice induced a shift from a brown to a white-like adipocyte phenotype, suggesting that Bmp4 may be an important factor in the context of obesity and type 2 diabetes." (PMID 31831718, 2019). "Furthermore, in a recently published gene therapy study, increased circulating BMP4 levels were shown to protect adult HFD-fed mice from obesity and improved their metabolic profile possibly due to increased browning of subcutaneous WAT17." (PMID 29222456, 2017). "BMP-4 were significantly decreased after Exenatide treatment in obesity." (PMID 28376799, 2017). "Therefore, further studies are required to investigate the relationship between serum BMP4 levels and the pathogenesis of obesity." (PMID 28376799, 2017). "However, obesity and cardiovascular disease are both multifactorial diseases, and BMP4 likely represents just one of numerous pathological mechanisms." (PMID 25678859, 2015). "However, if BMP4 cannot be upregulated because of genetic defects, metabolic failure related to obesity appears in aged and ovariectomized female mice, which is supported by the negative association between the BMP4 level and BMI identified in a cohort of female participants after menopause." (PMID 33872596, 2021). "Bone morphogenetic protein 4 (BMP4) may be an important factor in obesity and fatty liver." (PMID 33986800, 2021). "Furthermore, it has been shown that obesity is positively correlated with cellular BMP4 resistance, implying that BMP4 may participate in signaling pathways to control metabolic homeostasis." (PMID 32481541, 2020). "Visceral adipose mass may predict the serum BMP-4 levels in females with obesity." (PMID 28376799, 2017). "Therefore, in the current study, we compared the BMP-4 levels in obesity associated with different types of metabolic disorder to obesity without the corresponding complications." (PMID 28376799, 2017). "Besides, BMP-4 levels were slightly higher in obesity with Mets or hyperuricemia." (PMID 28376799, 2017). "We proposed that the excess adipose tissue associated with obesity might lead to negative feedback regulation of the BMP4-mediated adipocyte differentiation of pluripotent stem cells." (PMID 25678859, 2015). "Brain transcriptome analyses in obese mice identified several obesity-related pathways (e.g. leptin, somatostatin, and nemo-like kinase signaling), as well as genes involved in feeding and appetite (e.g. Pmch, Neurotensin) and in metabolism (e.g. Bmp4, Bmp7, Ptger1, Cox7a1)." (PMID 25629159, 2015). "For example, our recent genome wide association study (GWAS) of tooth emergence identified associations with variants in genes that have been implicated in obesity, HMGA2 and BMP4, suggesting a hitherto unrecognised link may exist between tooth emergence and obesity." (PMID 24823714, 2014). "Thus, BMP4 May be involved in both the promotion and suppression of obesity." (PMID 40028748, 2025). "In obesity, subcutaneous adipose tissue cells become BMP-4 resistant due to the secretion of the BMP-4 antagonist Gremlin-1, which then prevents beige/browning of subcutaneous adipose tissue (SAT)." (PMID 37518503, 2023).